EGFR (epidermal growth factor receptor)
Diseases named in the same sentence as EGFR in open-access papers (continued):
Sharing a sentence is not in itself a finding about the gene and the disease.
tumor (continued). "Recent changes to the prescribing guidelines for anti-EGFR mAbs (panitumumab and cetuximab) require RAS tumour genotyping to be carried out for patients with mCRC prior to the initiation of these therapies." (PMID 29183279, 2017). "The EGF binds to epidermal growth factor receptor (EGFR) to induce the expression of VEGF-A by triggering downstream Ras-MAPK, PI3K-Akt, and STAT signaling pathways, which play important roles in tumor growth and dissemination." (PMID 28486560, 2017). "The NOS inhibitor treatment also reduced EGFR expression and ERK2 phosphorylation level in the tumor tissues of xenograft mouse by using immunohistochemistry assay." (PMID 28380434, 2017). "Recent studies have shown that CUDC-101, a hybrid small molecule inhibitor targeting EGFR/HER2 and HDACs, shows significant anti-tumor effects in various types of cancer cells." (PMID 29113288, 2017). "EGFR and HER2 are the members of the HER family, whose EGF signaling pathway is known to play a crucial role in tumor initiation, progression and metastasis." (PMID 28187748, 2017). "TUNEL staining clearly showed apoptosis in xenograft tumor samples from mice treated by sonoporation in the presence of BLM and EGFR-MBs." (PMID 28938010, 2017). "The Met inhibitor SU11274 exerted a pro-apoptotic effect on EGFR-TKI-resistant H1975 cells and induced tumor regression in H1975 xenografts." (PMID 28619066, 2017). "Thus, while plasma is an inadequate substitute for tumor tissue in EGFR mutation tests, plasma testing could be used for tumor-tissue negative patients as an effective supplemental test." (PMID 28052016, 2017). "To evaluate the role of Tid1-S in mitochondrial EGFR accumulation and metastasis in vivo, we performed IF staining of EGFR, Tid1-S, and MTCOI in 35 paired tumor and adjacent normal tissues obtained from NSCLC patients of various stages." (PMID 28714950, 2017). "CQ-PCR also showed copy number variation of EGFR, normalized to the reference gene SPAG16, in the original tumor and derived cultures at various passages." (PMID 29113349, 2017). "One 1st-line/neoadjuvant trial using Dacomitinib (NCT0172833), a potent, irreversible kinase inhibitor of human EGFR/HER1, HER2 and HER4, has shown anti-tumor activity in N2-3 and M1 patients." (PMID 28813024, 2017). "We also found that the expression of EGFR in CRC tissues was positively correlated with the expression level of RPN2 and tumor size." (PMID 29069815, 2017). "Both EGFR and VEGFR-2 play a critical role in tumor growth, angiogenesis and metastasis, and targeting EGFR and VEGFR-2 simultaneously represents a promising approach to cancer treatment." (PMID 29295519, 2017). "For example, nitrosylation of several oncoproteins, including epidermal growth factor receptor (EGFR), Src and H-Ras, has been proposed to exert tumor-promoting effects." (PMID 28081246, 2017). "Paraffin-embedded tumor block of all TNBC patients were evaluated for CK5/6 and EGFR using IHC method." (PMID 28286613, 2017). "Here, we describe a total of 119 patients with advanced EGFR-TKI-naive NSCLC and 15 EGFR-TKI-resistant patients to identify somatic SNVs, small indels, CNVs and gene fusions in 508 tumor-related genes." (PMID 29097733, 2017). "18F-IRS accumulation was preferential in the tumor, which was NSCLC with responsive EGFR exon 19 deleted." (PMID 28600491, 2017). "Herein, we sought to assess the anti-proliferative, pro-apoptotic and anti-tumor activities of metapristone, a predominant metabolite of miferistone, against NSCLC cells with wild type EGFR (A549) or mutant type EGFR (H1975) both in vitro and in vivo." (PMID 29108234, 2017).
tumor (continued). "The oncogenic EGFR signaling in NSCLC engages the activation of downstream effectors such as AKT-mTOR, ERK and STAT3 to promote cell proliferation, cell survival, and tumor growth." (PMID 29177004, 2017). "FFJ-5, a naphthoquinone modifier of mollugin, attenuates the expression of PKM2 and reduces the production of ATP via blocking the EGFR-Akt-PKM2 pathway, which eventually induces tumor cell apoptosis." (PMID 29299177, 2017). "What’s more, metapristone inhibited the growth of NSCLC xenografts in BALB/c nude mice through decreasing the expression of tumor growth biomarkers PCNA and EGFR." (PMID 29108234, 2017). "The tetramerized bispecific antibody targeted EGFR and CD16 simultaneously and then exhibited cytotoxicity against EGFR-expressing tumor cells." (PMID 28931402, 2017). "The ErbB family of RTKs, which consist of Epidermal growth factor receptor (EGFR) (ErbB1 or HER1), ErbB2 (HER2 or Neu), ErbB3 (HER3), and ErbB4 (HER4), have been shown to promote tumor progression in various cancer types." (PMID 27902463, 2017). "Tumor-bearing animals were then treated with JNJ-61186372-LF, JNJ-61186372 IgG2σ (Fc-silent), EGFR-LF monovalent, c-Met-LF monovalent, or phosphate-buffered saline (PBS) vehicle control." (PMID 27786612, 2017). "Our findings enrich the complicated network of EGFR signaling and uncover a molecular mechanism of FLCN in tumor suppression." (PMID 29018350, 2017). "In this study, we investigated the expression profiles of CD73 and A2AR in tumor cells and found that both proteins were more strongly expressed in adenocarcinoma, particularly TTF-1-positive and EGFR-mutant adenocarcinomas." (PMID 28060732, 2017). "scFv:EGFR-TRAIL converted soluble TRAIL into a membrane-bound form, allowing efficient apoptosis in a series of EGFR-positive tumor cell lines." (PMID 31548531, 2017). "The EGFR/ERK/p38 MAPK pathway plays a crucial role in signal transduction in tumors, promoting tumor growth and migration at the transcriptional level." (PMID 28404978, 2017). "EGFR-PPARGC1A was found in keratinocytes, but also induced tumor formation in mouse fibroblasts NIH3T3, suggesting its potent tumorigenicity." (PMID 28978917, 2017). "Tumour growth was dramatically suppressed by the tumour-cell-vaccinated DCs; however, this antitumor effect was strongly attenuated by the cooperation of lnc-EGFR-infected CD4+ T cells, but was rescued by EGFR knockdown or lnc-EGFRΔR1." (PMID 28541302, 2017). "Although engagerEGFR inhibited EGFR signalling in vitro, mice treated only with PEG engagerEGFR displayed similar tumour growth as mice treated with PBS." (PMID 28593948, 2017). "Although the prior gold standard of Sanger sequencing covers all EGFR mutations within exons 18–21, it’s analytic sensitivity (20–40% tumor cellularity) may not be adequate in the clinical diagnostic setting where specimens containing low tumor cellularity are not uncommon." (PMID 29228562, 2017). "Cetuximab therapy is accomplished through increasing tumour-specific CTL activity and reducing Tregs42, thus revealing a link between EGFR and Tregs." (PMID 28541302, 2017). "In order to effectively achieve EGFR-targeted NIR-PTT for MDA-MB-231 tumor treatment, we excluded the GN+NIR-PTT group from the in vivo study and selected an NIR-PTT treatment time of 48 h after anti-EGFR-GN injection." (PMID 29156817, 2017). "Next, tumor lysates were immunoprecipitated with anti- αvβ3 LM609 antibody and immunoblotted with anti-EGFR antibody." (PMID 28425453, 2017). "Cetuximab, as an EGFR inhibitor, can block the combination between EGFR and its ligands competitively, such as epidermal growth factor (EGF), resulting in inhibition of growth, invasion, and metastasis of tumor cells." (PMID 29390545, 2017).
tumor (continued). "Various established membrane-bound tumour markers are under evaluation as targets for (NIR) fluorescence imaging in pre-clinical settings, such as EGFR, HER2/Neu, VEGF(R), folate receptor alpha, uPAR and various integrins." (PMID 27842504, 2016). "Lapatinib targets the epidermal growth factor receptor (ErbB1) and the related family member HER-2/neu (ErbB2) on the cell surface of the tumor cells." (PMID 27108407, 2016). "The most common signaling cascades activated downstream of EGFR are PI3K/Akt, Ras/Raf/Mek and DAG/IP3 and CaM signaling, that affect cell cycle progression, inhibition of apoptosis, angiogenesis, tumor cell motility, and metastases." (PMID 27253373, 2016). "Among these, EGFR and HER2 co-amplification was detected in 8/14 tumours (3.6 % of the whole study material)." (PMID 27387915, 2016). "The three drugs that were initially selected on the basis of their reactivity toward the EGFR-RAF-MEK-ERK pathway, i.e., cetuximab, erlotinib and sorafenib, displayed neighbouring activity in terms of effect on tumour cell proliferation in HNSCC." (PMID 27085492, 2016). "The QMP images of EGFR and HER2 expression in various tumor xenografts show excellent quantitative agreement with corresponding flow-cytometry results (R > 0.98)." (PMID 26878888, 2016). "In SK-N-MC tumor xenografts, ERBB4 and EGFR were the prominent RTKs detected by the phospho-proteome array together with INSR and IGF1R." (PMID 27374103, 2016). "We demonstrated that the resulting PSEP chimera specifically and effectively suppresses the endogenous expression of EGFR and survivin in PCa cells expressing PSMA, and significantly inhibits tumor growth in mouse models." (PMID 27456457, 2016). "For this reason it would be particularly interesting to study a combination therapy with EGFR and RTK-AXL inhibitors to exhibit synergistic effect with respect to tumor control and treatment response." (PMID 26848524, 2016). "EGFR gene amplification was found in 31/72 tumours (14.1 % of the whole study material) and HER2 gene amplification in 29/31 tumours (13.2 % of the whole study material)." (PMID 27387915, 2016). "Here, the authors sequence circulating tumour DNA and show that resistance to the third-generation inhibitor rociletinib is heterogeneous and recurrently involves somatic alterations of MET, EGFR, PIK3CA, ERRB2, and KRAS." (PMID 27283993, 2016). "However, monoclonal antibodies targeting VEGF and EGFR may be un-sufficient to controlling the activity of other signaling pathways such as IL6/STAT3 signaling, which may exemplify the underlying mechanism of anti-tumor resistance." (PMID 27729020, 2016). "One tumor exhibited high-level amplification of a component with two low-level amplifications (high FGFR2/low KRAS and EGFR amplification in one case)." (PMID 27014419, 2016). "The epidermal growth factor receptor (EGFR) signaling cascade is one of the key signaling pathways that are involved in the induction of Epithelial Mesenchymal Transition (EMT) and tumor metastasis." (PMID 27253373, 2016). "There are also correlations between the EGFR and VEGF pathways, as these share parallel and reciprocal downstream signaling mechanisms, and exert direct and indirect effects on tumor cells that contribute to cancer progression." (PMID 27245053, 2016). "Immunohistochemical (IHC) analysis was conducted on FFPE tumor to investigate IGF-1R and EGFR expression, using an IGF-1R IHC protocol recently optimized for sensitivity and specificity." (PMID 27200287, 2016). "The objective of this study was to compare the plasma analysis performed using PANAMutyperTM R EGFR and KRAS kits with tumor tissue analysis performed using routine EGFR and KRAS mutation tests." (PMID 27519791, 2016).
tumor (continued). "Compared with the normal-looking regions, overexpression of EGFR and SHP2 increased with tumor progression." (PMID 26728598, 2016). "In this study, we evaluated the heterogeneity of MET and EGFR expression in primary and metastatic TNBC tumorgrafts and evaluated the efficacy of MET and EGFR inhibition against tumor growth." (PMID 27655711, 2016). "We revealed that EGFR expression’s slight correlations with age, gender, CA19-9, and tumor site, size, stage, and grade." (PMID 27399694, 2016). "To identify the effect of soluble c-Met dynamic change on the resistance to EGFR-TKI, we divided the 49 patients into two groups according to c-Met status in the tumor tissue with PD." (PMID 27213587, 2016). "The human epithelial growth factor receptors EGFR, HER2 and HER3 have been studied in several tumour types, and HER-targeting drugs have a beneficial effect on survival in selected types of cancer." (PMID 27070783, 2016). "Similar with EGFR and C-met, the activation of her3, the preferred dimerization partner of HER2, also plays a key role in driving HER2-amplified tumor growth." (PMID 28036020, 2016). "Previous studies of acquired MET inhibitor resistance in several tumor types, including NSCLC, suggest that de novo dependence on EGFR signaling is a common means to circumvent MET inhibition." (PMID 27472392, 2016). "Taken together, the GABARAP family proteins mediates trafficking and surface expression of receptors with both tumor promoting (EGFR, GABAAR) and tumor inhibitory characteristics (KOR)." (PMID 27933272, 2016). "The impact on the outcome of upcoming third generation EGFR-TKI therapy era due to the discrepancy between plasma and rebiopsy tumor T790M status requires further evaluation." (PMID 27384480, 2016). "Constitutively, activated state of EGFR, HER-2, and HER-3 in epithelial tumors consequence in aggressive tumor behaviors like initiation and extension of tumor growth, metastasis and chemoresistance, finally results into poor patient outcome." (PMID 27051190, 2016). "Thus, in the case reported here, the lack of EGFR expression on CTC could be also related to a rare mutated tumor type." (PMID 27465596, 2016). "We examined EGFR and ALK expression in the tumor cells and the effect of erlotinib and crizotinib on the phosphorylation of EGFR and ALK by Western blotting." (PMID 27070423, 2016). "EGFR and its downstream pathway regulate epithelial–mesenchymal transition (EMT), migration, and tumor invasion." (PMID 27557521, 2016). "Moreover, these guidelines also stressed the existence of accumulating evidence that patients with a BRAF mutated tumour might not benefit from anti-EGFR therapy, raising the possibility that BRAF mutation has predictive value." (PMID 27999270, 2016). "In addition to EGFR, the levels of mRNA encoding for the other members of the ErbB family, including ErbB2 and ErbB3, showed a decrease rather than an increase in all resistant tumor cell lines." (PMID 27248176, 2016). "Ligand-induced EGFR activation plays a key role in tumor proliferation, invasion, and migration through the RAS-RAF-MAPK and PI3K-AKT-mTOR pathways, and ligand binding results in EGFR activation in cell lines." (PMID 27344184, 2016). "Furthermore, we found that high LDH serum level was an independent predictor of PFS and OS in patients with the EGFR mutation; this may have been because serum LDH level is related to intratumoral angiogenesis, tumor invasion ability, and resistance to therapy." (PMID 27336755, 2016). "To optimize EGFR-PET, we examined the influence of sEGFR levels on tracer kinetics and tumor uptake of EGFR monoclonal antibody 89Zr-imgatuzumab in varying xenograft models." (PMID 27602494, 2016).
tumor (continued). "The observed co-expression of RET and EGFR in MLS prompted further investigation of RTKs as possible drug targets and their role in tumor development." (PMID 26595521, 2016). "Immunohistochemical expression of EGFR and HER3 was analysed in all primary tumours and a subset of lymph node metastases in a consecutive cohort of 174 patients with adenocarcinoma of the stomach, cardia and esophagus." (PMID 26844548, 2016). "The qRT-PCR based panel of MYC, MYCN, CCND1, CCND2, EGFR and FNDC3A was successful in detecting neoplasia with an overall accuracy of 54 % in S-CRN compared to that of 29 % in UC neoplastic samples." (PMID 27080994, 2016). "Each mouse was carrying two tumours: an A431 tumour with high EGFR/CD44v6 expression in the left flank and a UM-SCC74B tumour with low EGFR/CD44v6 expression in the right flank." (PMID 26627081, 2016). "Injection of EGFR knockout HCT116 cells reduced tumor growth, and injection of Ana-1 cells with either HCT116 or HCT116 KO-EGFR cells increased tumor growth." (PMID 27683110, 2016). "EGFR and HER2 have been shown to be involved in tumour growth and metastasis of IBC, and as such represent therapeutic targets." (PMID 27923043, 2016). "The chemotherapy drug Erlotinib targets the intracellular domain of EGFRvIII and EGFR, and thus the intervention by Erlotinib would presumably block EGFR related pathways such as PI3K pathway and inhibit tumor aggressiveness." (PMID 27581736, 2016). "In our material, EGFR gene amplification was most common in the tumours of distal oesophagus and GOJ/cardia, as observed in the CIN subgroup, but infrequent in the tumours of gastric corpus." (PMID 27387915, 2016). "In most Oncomine data sets with lower tumour ZEB1, the expression levels of both EGFR and KRAS were marginally higher in tumours compared with paired normal lung tissues." (PMID 27456471, 2016). "Mice that received either EGFR-CAR NK-92, oHSV-1, or their combination had significantly reduced tumor growth compared to those injected with mock-transduced NK-92-EV or vehicle (HBSS)." (PMID 27050072, 2016). "To assay TKI-induced anti-tumor responses we used EGFRL858R and the EGFR downstream pathway proteins, ERK1/2 (phospho-ERK1/2 Thr 202/Tyr 204), AKT (phospho-AKT Thr 308) and a signal transducer and activator of transcription 3 (phospho-STAT3 Tyr 705)." (PMID 27494838, 2016). "We have earlier reported a strong up-regulation of EGFR and p16, including H-, K- and N-RAS, and in the present mRNA analysis all of these tumour genes were strongly correlated." (PMID 27465361, 2016). "Multivariate analysis demonstrated that vascular endothelial growth factor (VEGF) (P = 0.002), epidermal growth factor receptor (EGFR) (P = 0.001), and TWIST2 (P = 0.001) expression levels, as well as a tumor size <6 cm (P = 0.02), influenced OS." (PMID 27230280, 2016). "Among these factors are the epidermal growth factor (EGF) and its receptor (EGFR) and the vascular endothelial growth factor (VEGF) and its receptor (VEGFR), which constitute key elements in tumor growth and dissemination." (PMID 27806094, 2016). "Recent studies have also implicated modulation of the multidrug resistance protein (MDR1), epidermal growth factor receptor (EGFR) and tumor initiating cells in order to facilitate complementary action with both targeted and cytotoxic therapeutics." (PMID 27633667, 2016). "Quantitative real-time polymerase chain reaction confirmed the overexpression of EGFR and KDR genes in the tumor tissue." (PMID 27149458, 2016).